VEGFC (vascular endothelial growth factor C)
Diseases named in the same sentence as VEGFC in open-access papers (continued):
Sharing a sentence is not in itself a finding about the gene and the disease.
atherosclerosis (21 papers, 2011 to 2025). A disease characterized by the build-up of fatty material and calcium deposition in the arterial wall resulting in partial or complete occlusion of the arterial lumen. "For example APOE deficient mice are prone to atherosclerosis, but C3 modulation of lipid metabolism can protect them, while VEGFC is a marker for advanced atherosclerosis and hypercholesterolemia in the same animals." (PMID 27112350, 2016). "VEGFC-156S treatment enhanced lymphangiogenesis without affecting hypercholesterolemia but did not improve lymphatic drainage, reduce plasma cholesterol, and atherosclerosis lesion size." (PMID 34072313, 2021).
lung adenocarcinoma (20 papers, 2003 to 2025). A carcinoma that arises from the lung and is characterized by the presence of malignant glandular epithelial cells. "A recent study revealed that vascular endothelial growth factor C (VEGF‐C) is closely associated with EGFR‐TKI resistance in lung adenocarcinoma." (PMID 37605832, 2023). "In conclusion, both high VEGFC and PD‐L1 expression indicate a poor prognosis in lung adenocarcinoma patients, and VEGFC is positively correlated with PD‐L1." (PMID 32154654, 2020). "Co‐expression of VEGFC and PD‐L1 may serve as a significant prognostic factor for patients with lung adenocarcinoma." (PMID 32154654, 2020). "Furthermore, the expression levels of ANXA1, VEGFC, PDGFC and LRRN3 were significantly positively associated with the survival of lung adenocarcinoma." (PMID 33293474, 2020). "In addition, our study also provides the theoretical possibility to screen the optimal population with a combination of anti‐VEGFC and anti‐PD‐L1 therapy in lung adenocarcinoma." (PMID 32154654, 2020). "Moreover, the expression of VEGFC and PDGFC was associated with longer survival time of lung adenocarcinoma patients." (PMID 33293474, 2020). "VEGFC/PD‐L1 co‐expression forecasts poor survival in patients with resected lung adenocarcinoma." (PMID 32154654, 2020). "The prognosis of patients with lung adenocarcinoma was significantly affected by six genes (KRT6A, VEGFC, KRT14, KRT17, SNORA12, and KRT81) related to FSTL3." (PMID 38240936, 2024). "Taken together, these results indicate that VEGFC/PD‐L1 co‐expression can forecast both poor OS and PFS in patients with resected lung adenocarcinoma." (PMID 32154654, 2020). "A significant mRNA down-expression of VEGFC and VEGFD has been reported in human lung adenocarcinomas." (PMID 29137669, 2017). "Concurrently, we will delve into the interactions between FSTL3 and other pertinent genes, such as KRT6A, VEGFC, KRT14, KRT17, SNORA12, and KRT81, to enhance our understanding of its role in lung adenocarcinoma progression and to pinpoint novel therapeutic targets." (PMID 38240936, 2024). "Nevertheless, the clinical significance of co‐expression of VEGFC and PD‐L1 for predicting outcomes in patients with lung adenocarcinoma has not yet been determined." (PMID 32154654, 2020). "We identified four biomarkers (MAP3K8, CCL20, VEGFC, and ANGPTL4) that could predict overall survival in lung adenocarcinoma (HR = 1.98, 95% CI 1.48 to 2.64, P = 4.19e−06) and this model could be used as a classifier for the evaluation of low-risk and high-risk groups." (PMID 32019546, 2020).
myocardial infarction (20 papers, 2019 to 2025). Gross necrosis of the myocardium, as a result of interruption of the blood supply to the area, as in coronary thrombosis. "In myocardial infarction models, VEGFC secreted by proinflammatory macrophages drives lymphangiogenesis and extensive remodeling of the cardiac lymphatic network, maintaining immune cell homeostasis and effective tissue repair during postinfarction healing." (PMID 37762426, 2023). "In mouse models of myocardial infarction, treatment with adrenomedullin or a recombinant form of VEGFC that selectively activates VEGFR3 has led to the resolution of disease-induced edema and inflammatory factors, successfully averting cardiac fibrosis and dysfunction." (PMID 41221452, 2025). "Similarly, in myocardial infarction (MI), VEGFC secreted by macrophage-driven lymphangiogenesis promotes cardiac infarct healing as well as tissue repair." (PMID 37762426, 2023). "For instance, phagocytic clearance of dying cells directly induces the transition of cardiac macrophages into a phenotype with enhanced expression of vascular endothelial growth factor (VEGF) C, and macrophage-derived VEGFC inhibits inflammation after myocardial infarction." (PMID 37601043, 2023). "Intraperitoneal injection of recombinant VEGFC-C156S, intramyocardial injection of microparticles loaded with VEGFC-C156S, and intraperitoneal injection of adeno-associated virus (AAV) encoding VEGFC-C156S all showed robust protective effects after myocardial infarction." (PMID 35461308, 2022). "In the myocardial infarction (MI) model, CD11b+ and CD36+ macrophages also express VEGFC to promote cardiac lymphangiogenesis and protect cardiac function." (PMID 36831512, 2023). "Blockade of VEGFC signaling by soluble VEGFR3 (sVEGFR3) leads to impaired cardiac lymphoid morphology and increased mortality due to myocardial infarction in mice." (PMID 37762426, 2023). "Klotz and colleagues find that vascular Endothelial Growth Factor C (VEGF-C) induce a stronger lymphangiogenic response and result in improved cardiac function after myocardial infarction." (PMID 33821373, 2021). "VEGF-C has been identified as a key molecule in cardiac angiogenesis and lymphangiogenesis through the activation of the VEGFC/VEGFR-3 pathway, leading to the improvement of cardiac function after myocardial infarction." (PMID 32936824, 2020). "VEGFC, which is listed in S2 Table as a gene upregulated in VCFs, is involved in cardiac lymphangiogenesis through the activation of the VEGFC/VEGFR-3 pathway leading to the improvement of cardiac function after myocardial infarction." (PMID 32936824, 2020).
thyroid cancer (18 papers, 2006 to 2023). "Rg3 inhibits thyroid cancer metastasis by suppressing vascular endothelial growth factor-C (VEGF-C) protein expression in PTC cells and VEGF-A protein expression in anaplastic thyroid cancer (ATC) cells." (PMID 37571224, 2023). "Comparing VEGF/VEGFR subunit expressions among thyroid cancer and other cancer types, the result clearly showed that the mean log2 fluorescence intensity of VEGFC was 9.08 ± 0.71 in thyroid cancers and 6.66 ± 0.084 in other cancer types (5.33‐fold, P = 0.002)." (PMID 35313079, 2022). "Interaction of SRC-1 with p50/p65 drives the expression of Vascular Endothelial Growth Factor C (VEGFC) in a thyroid carcinoma cell line TPC-1, while KD of SRC-1 results in a decrease of VEGFC transcription and expression." (PMID 36582250, 2022). "An analysis of expression levels identified a positive correlation between SRC-1 and VEGFC levels in the thyroid cancer tissues, and showed that SRC-1 levels were positively associated with VEGFC expression in the tumors (r2 = 0.6756; 95% CI: 0.4536–0.8187)." (PMID 29717026, 2018). "The levels of SRC-1 expression in samples of thyroid cancer tissue, and their correlation with VEGFC levels and LYVE-1-positive lymphatic vessels were analyzed." (PMID 29717026, 2018). "We found that SRC-1 was up-regulated in thyroid cancer tissues and interacted with NF-kB signals to promote VEGFC expression and increase the numbers of LYVE-positive lymphatic vessels." (PMID 29717026, 2018). "In the present study, we revealed how SRC-1 promotes tumorigenesis by participating in VEGFC-induced lymphangiogenesis in cases of thyroid cancer." (PMID 29717026, 2018). "Knockdown of SRC-1 in thyroid cancer in vivo inhibited VEGFC expression, which led to a reduction in lymphangiogenesis." (PMID 29717026, 2018). "However, the molecular mechanisms of VEGFC-induced lymphangiogenesis are not fully known in thyroid cancer." (PMID 29717026, 2018). "However, the correlation between SRC-1 and VEGFC levels in the lymphatic metastases of thyroid cancer remains unclear." (PMID 29717026, 2018). "High expression of VEGFA and VEGFC showed favorable responses to various drugs, including BLU-667, which abrogates RET signaling, an oncogenic driver in liver and thyroid cancers." (PMID 37852616, 2023). "In Thyroid carcinoma (THCA), most of the VEGF family genes, except VEGFC, were differentially expressed in different tumor stages." (PMID 37852616, 2023). "Here, we show that both VEGFC and VEGFR2/KDR are overexpressed in thyroid cancers, indicating that VEGF/VEGFR signaling plays a carcinogenic role in thyroid cancer development." (PMID 35313079, 2022). "In thyroid cancer cell lines (FTC-133 and CGTH-W-1), PROX1 and VEGFC are expressed, and in CGTH-W-1 cells, VEGFC was oppositely regulated by PROX-1 knockdown, which enhanced the VEGFC expression level and its secretion." (PMID 32370142, 2020). "The regulatory mechanism of SRC-1/VEGFC was determined in vitro and the role played by SRC-1 in thyroid cancer was investigated in vivo." (PMID 29717026, 2018). "Furthermore, an immunohistochemistry analysis confirmed that the proteins SRC-1/VEGFC (positive: 13/20 and positive: 15/20) and SRC-1/LYVE-1 (positive: 13/20 and positive: 18/20) were highly expressed in a majority of thyroid cancer specimens." (PMID 29717026, 2018). "Similarly, we found that in thyroid cancer, SRC-1 interacts with NF-kB (p65) to form a co-activation complex that induces transcription of the VEGFC gene in TPC-1 cells." (PMID 29717026, 2018). "We analyzed 20-paired specimens of thyroid cancer tissue and normal thyroid tissue and found increased levels of SRC-1 and VEGFC proteins in 13/20 and 15/20 thyroid cancer specimens, respectively, when compared with those levels in specimens of normal thyroid tissue." (PMID 29717026, 2018).
chondrosarcoma (17 papers, 2013 to 2024). A malignant cartilaginous matrix-producing mesenchymal neoplasm arising from the bone and soft tissue. "CCL5 has also been shown to promote VEGFC production and induce lymphangiogenesis via suppressing miR‐507, which binds to 3′UTR of the VEGFC gene, in human chondrosarcoma cells." (PMID 33128283, 2021). "Combo), a chemokine shown promote lymphangiogenesis through upregulation of VEGFC expression by chondrosarcoma cells." (PMID 29976154, 2018). "Further, BDNF administration increases miR-214 expression during embryonic stem cell differentiation into endothelial cells, and it is found to promote vascular endothelial growth factor-C-dependent lymph angiogenesis by suppressing miR-624-3p in human chondrosarcoma cells." (PMID 38786102, 2024).
Insulin resistance (17 papers, 2011 to 2025). Increased resistance towards insulin, that is, diminished effectiveness of insulin in reducing blood glucose levels. "Notwithstanding, repression of VEGFC might be beneficial since its overexpression caused insulin resistance and weight gain in transgenic mice." (PMID 39962359, 2025).
Obesity (17 papers, 2016 to 2024). Accumulation of substantial excess body fat. "As elevated VEGFC is associated with obesity and overexpression of Vegfc promotes fat mass gain and insulin resistance, the reduced weight gain and improved metabolic profile we observed in the Adamts14−/− mice, could be caused via a reduction of VEGFC levels, concordant with other published models." (PMID 36658113, 2023). "VEGFC and -D are elevated in adipose tissue during obesity and an overexpression of VEGFD in adipose tissue resulted in de novo lymphatics and improved overall metabolism in mice." (PMID 34200994, 2021). "The lymphangiogenic proteins vascular endothelial growth factor C (VEGF-C) and –D (VEGF-D), ligands for VEGFR-3, are elevated in adipose tissue during obesity." (PMID 32390866, 2020).
Hypertension (16 papers, 2010 to 2025). The presence of chronic increased pressure in the systemic arterial system. "In the present study, we found that Ang II‐induced hypertension inhibited lymphangiogenesis and down‐regulate the expression of lymphatic markers in mice hearts and decrease VEGFC in their serum, and SIRT3‐KO further suppressed these processes." (PMID 34180125, 2021). "The relationship between skin deposition of sodium and hypertension may be mediated by a molecular mechanism in which vascular-endothelial growth factor-C (VEGF-C) is the most relevant mediator." (PMID 31438636, 2019). "Furthermore, these effects are not limited to salt-induced pathology, as VEGFCc156s also ameliorated angiotensin II-induced hypertension and renal damage, suggesting that VEGFC may play a broad role to modulate hypertension." (PMID 33200983, 2020). "Our observations are in line with a previous report indicating that the treatment of VEGFC, a ligand for both VEGFR2 and VEGFR3, also induced a delayed systemic hemodynamic response to reduce blood pressure and attenuated related renal damage in a high-salt induced hypertension model." (PMID 33200983, 2020).
oral squamous cell carcinoma (16 papers, 2012 to 2025). "The elevated expression of FN1 promotes lymph node metastasis in human oral squamous cell carcinoma by promoting vascular endothelial growth factor-C expression and the epithelial–mesenchymal transition (EMT)." (PMID 30237810, 2018).
breast tumors (14 papers, 2005 to 2025). "It is very well known that COX-2 induces angiogenesis and lymphangiogenesis through production of VEGFC and VEGFD, and upregulation of PI3K/Akt signalling and COX-2 overexpression can also induce LYVE-1 over expression in mouse breast tumours." (PMID 31277414, 2019).
endometriosis (14 papers, 2018 to 2025). The growth of functional endometrial tissue in anatomic sites outside the uterine body. "Based on these outcomes, we can infer that BST2 can regulate the transcription of VEGFC via the NF-κB signaling pathway, thereby promoting lymphangiogenesis in endometriosis." (PMID 37143676, 2023). "VEGFC acted as a critical modulator of the progression of endometriosis by promoting lymphangiogenesis." (PMID 37143676, 2023). "In particular, vascular endothelial growth factor C (VEGF-C) plays an important role in the angiogenesis mechanism and also serves as a potential therapeutic target of anti-angiogenesis for endometriosis." (PMID 34449536, 2021). "ClusterB was revealed to be associated with significantly overexpressed VEGFA and VEGFC and, notably, downregulated ESR1 and PGR, which are characteristic biomarkers of endometriosis, indicating that clusterB might be highly linked to endometriosis." (PMID 36672827, 2022). "EGCG selectively inhibits the expression of vascular endothelial growth factor VEGF-C (VEGFC) and the tyrosine kinase receptor, VEGFR2, by inhibition of the VEGFC/VEGFR2 signaling pathways, which inhibits endometriosis-associated angiogenesis of endothelial cells." (PMID 30402122, 2018). "VEGFC acts on endothelial cells and promotes early angiogenic responses through the VEGFR2-mediated pathway, which promotes endothelial function and endometriosis vascular permeability." (PMID 30402122, 2018). "First, EGCG was found to downregulate the expression of pro-angiogenic factors like vascular endothelial growth factor A (VEGF-A), vascular endothelial growth factor C (VEGF-C), and the tyrosine kinase receptor VEGF receptor 2 (VEGFR2) in murine endometriosis models." (PMID 36986169, 2023).
colitis (13 papers, 2016 to 2025). Inflammation of the colon. "Furthermore, VEGFC aggravates intestinal inflammation in mice with experimental colitis and is associated with inflammatory lymphatic formation." (PMID 35865663, 2022). "The promote relationships between TNF-α and Vascular Endothelial Growth Factor-C (VEGF-C), ARRB1 and VEGF-C has been confirmed in many diseases including pulmonary hypertension, colitis and gallbladder cancer 22-24." (PMID 33753990, 2021).
inflammatory bowel disease (13 papers, 2015 to 2025). A spectrum of small and large bowel inflammatory diseases of unknown etiology. "Stimulation of lymphatic function by vascular endothelial growth factor-C ameliorated inflammatory bowel disease in mice." (PMID 30013036, 2018). "Moreover, a VEGFC and VEGFR3 axis regulates macrophage plasticity in association with the amelioration of experimental inflammatory bowel disease." (PMID 35271504, 2022). "Wang X found that VEGFC plays a vital role in the pathogenesis for inflammatory bowel diseases (IBD), which aggravated intestinal inflammation through stimulation." (PMID 31191213, 2019).
Stroke (13 papers, 2013 to 2026). Sudden impairment of blood flow to a part of the brain due to occlusion or rupture of an artery to the brain. "In a stroke mouse model, intrathecal or intracerebroventricular prophylactic delivery of viral-encoded VEGFC increased lymphatic drainage and, thus, promotes neuroprotective signaling and neurological recovery." (PMID 40050849, 2025). "Another aspect of the peripheral immune response to stroke involves cervical lymph node hypertrophy, likely from CNS drainage coupled with the large-scale release of vascular endothelial growth factor C (VEGF-C)." (PMID 40356948, 2025). "A photothrombotic ring stroke rat model demonstrated that VEGFC promotes early angiogenesis, leading to spontaneous reperfusion after stroke." (PMID 36118760, 2022). "VEGFC has demonstrated neuroprotective effects in PD and stroke models." (PMID 40050849, 2025). "Overall, main FD features including hypertrophic cardiomyopathy, venous thrombosis, arterial thrombosis, and stroke, cornea verticilata, and renal (chronic kidney disease stage) events are partly explained by FGF2, IL-7, VEGFA, and VEGFC plasma levels." (PMID 32370284, 2020).
metastasis (12 papers, 2003 to 2021). The spread or migration of cancer cells from one part of the body (where they first appeared) to another. "mTOR inhibitors decreased VEGFC/D expression and diminished lymphangiogenesis and lymph node metastasis in various cancer models." (PMID 33128283, 2021).
oral cancer (12 papers, 2013 to 2023). "For instance, polymorphisms of the vascular endothelial growth factor C (VEGF-C) gene can predict the risk and prognosis of various diseases, including urothelial cell carcinoma, oral cancer, and coronary artery disease 17-19." (PMID 31692815, 2019). "In oral cancer, HMGB1 has been reported to promote lymphangiogenesis through the upregulation of vascular endothelial growth factor C (VEGF-C) and vascular endothelial growth factor D (VEGF-D), which might be linked to the transmigration of HMGB1." (PMID 25622595, 2015).
renal cell carcinoma (12 papers, 2009 to 2024). "It was later shown that the anti-angiogenic drug sunitinib, which inhibits multiple receptor tyrosine kinases, induces lymphangiogenesis in renal cell carcinoma (RCC) by inducing VEGFC expression which was associated with increased LN metastasis." (PMID 34568423, 2021). "VEGFC is involved in two signaling pathways: renal cell carcinoma and mTOR." (PMID 26571238, 2015).
hepatocellular carcinoma (10 papers, 2012 to 2025). A malignant tumor that arises from hepatocytes. "Another study revealed that hsa-miR-101-3p inhibited cell migration by suppressing VEGFC expression in hepatocellular carcinoma." (PMID 37852616, 2023). "Hepatocellular carcinoma (HCC) is associated with lymphangiogenesis and expression of the vascular endothelial growth factor C (VEGF-C) correlates with size and metastasis formation of HCC." (PMID 36051444, 2022).